PTH (parathyroid hormone)
Diseases named in the same sentence as PTH in open-access papers (continued):
Sharing a sentence is not in itself a finding about the gene and the disease.
osteoporosis (continued). "We report the monitoring of PTH treatment efficacy, when given as a preventive drug and as a treatment for severe osteoporosis in an animal model." (PMID 28638673, 2017). "The increase of PTH affects bone deposition and further leads to the decrease of BMD, which increases the incidence risk of osteoporosis." (PMID 28686649, 2017). "Vitamin D was negatively correlated with PTH in all subjects (r = −0.295, p < 0.01) as well as in osteoporosis subjects (r = −0.30, p < 0.01)." (PMID 28124221, 2017). "The levels of PTH, HbA1c and diabetes duration were all significantly higher in osteoporosis group than osteopenia group and normal BMD group (P<0.05), whereas 25OHD also presented a downward trend in osteopenia group and osteoporosis group." (PMID 29190676, 2017). "PTH, the only anabolic treatment for osteoporosis in postmenopausal women that is approved by the FDA, has been found in both animal and clinical research to enhance fracture healing." (PMID 28279202, 2017). "In both clinical observations and animal experiments, previous studies have shown that intermittent PTH can prevent osteoporosis of the vertebra body or long bones." (PMID 28438150, 2017). "Teriparatide (recombinant human parathyroid hormone), an anabolic agent for osteoporosis, produces the largest increase in bone mineral density, when compared to that of any other osteoporosis treatment." (PMID 28955232, 2017). "Parathyroid hormone (PTH) is clinically used to treat osteoporosis because it has anabolic effects on bone formation though activating osteoblasts." (PMID 29259706, 2017). "The primary endocrine factors involved in the development of osteoporosis are parathyroid hormone (PTH), vitamin D, calcitonin, and estrogen." (PMID 29163183, 2017). "Medications like bisphosphonates, vitamin D, calcitonin, teriparatide, parathyroid hormone, infliximab, and denosumab are effective for the prevention and treatment of osteoporosis." (PMID 28913325, 2017). "Similar to previous animal experiments, the present study found that intermittent PTH effectively treated OVX-induced osteoporosis." (PMID 28438150, 2017). "It is expected that these results will be confirmed in patients with osteoporosis treated with IBN after withdrawal of PTH." (PMID 28246925, 2017). "In conclusion, the results of our study suggest that continual intermittent PTH administration is effective for achieving favorable primary and secondary stability in the presence of osteoporosis." (PMID 29069147, 2017). "This study aimed to evaluate the effects of continual intermittent administration of parathyroid hormone (PTH) on implant stability in the presence of osteoporosis, using rabbit models." (PMID 29069147, 2017). "Bisphosphonates (BPs) and parathyroid hormone (PTH) are antiresorptive and bone anabolic agents, respectively, and both are clinically effective treatments for osteoporosis." (PMID 28948197, 2017). "Recombinant human parathyroid hormone (PTH) is the key anabolic agent used for preventing fracture in postmenopausal women with osteoporosis." (PMID 30283879, 2017). "BPs therapy should be stopped in men with severe osteoporosis who are intolerant or unresponsive to BPs therapy after one year, and PTH therapy should be selected as an alternative." (PMID 28173850, 2017). "Teriparatide, the 1–34 portion of parathyroid hormone (PTH), has been approved by the US FDA for use as an anabolic agent in the treatment of adults with severe osteoporosis, who are at high risk for fractures." (PMID 28279202, 2017). "Serum IL-1β, IL-6, NTx, and PTH levels in women with osteoporosis were significantly higher than controls." (PMID 28121926, 2017). "Teriparatide (TPD, recombinant human parathyroid hormone (PTH) 1–34), an osteogenic osteoporosis agent, has been used increasingly for patients with severe osteoporosis and at high risk of fractures." (PMID 28388910, 2017).
osteoporosis (continued). "PTH has uniqueness in being a real anabolic agent, while osteoporosis medicaments that have been used are antiresorptive agents." (PMID 28280735, 2017). "Parathyroid hormone is a prototypic osteoanabolic hormone for treating osteoporosis when given as a daily injection." (PMID 29127344, 2017). "When given once daily, parathyroid hormone (PTH), is the only approved osteoporosis treatment agent that stimulates new bone formation." (PMID 27759007, 2016). "Parathyroid hormone (PTH) is an endogenous hormone and osteoporosis therapeutic that suppresses sclerostin activity." (PMID 27759007, 2016). "Currently, the long-term administration of teriparatide, a synthetic form of PTH, in low doses represents one of the treatment options for osteoporosis." (PMID 27957280, 2016). "Anti-osteoporosis includes selective estrogen receptor modulators, bisphosphonates, and parathyroid hormone analogs." (PMID 27052323, 2016). "In contrast, the only bone anabolic agent currently marketed for treating osteoporosis is the human parathyroid hormone (PTH) analogue teriparatide." (PMID 26968635, 2016). "Given the chronic nature of hypoparathyroidism and osteoporosis, orally active PTH mimetics are desirable and will benefit patients in their long-term treatment." (PMID 27857062, 2016). "While PTH is widely used in treating osteoporosis, many studies have reported that it contributes to improvement of fracture healing." (PMID 26926165, 2016). "While PTH agents are widely used for osteoporosis, it has been reported that they enhance the early chondrogenic stages of endochondral bone formation." (PMID 26926165, 2016). "Medications for osteoporosis are generally anti-resorptive reagents acting on osteoclasts and the modulators of estrogen, calcitonin, and parathyroid hormone to increase blood Ca2+ concentration." (PMID 26999128, 2016). "In patients on dialysis, high parathyroid hormone level and osteoporosis predict progression of CAC; and bone volume/total volume (BV/TV) assessed by HR-pQCT were significantly lower in patients with CAC scores ≥100." (PMID 27042671, 2016). "Calcilytics' failure as therapeutics for osteoporosis due to the double-edged effects of PTH was a stroke of ill-luck." (PMID 27199760, 2016). "Hypoparathyroidism and osteoporosis can be treated with parathyroid hormone, but frequent injections are required." (PMID 27857062, 2016). "Teriparatide comprises AA sequence 1–34 of human parathyroid hormone, and it is used to treat postmenopausal women with osteoporosis." (PMID 27353345, 2016). "The one case treated with recombinant human parathyroid hormone had failed several earlier therapies for osteoporosis." (PMID 26064078, 2015). "The proportions of patients treated with anti-osteoporosis drugs and parathyroid hormone were significantly higher in the BMD <70 % of YAM group." (PMID 26420629, 2015). "On the other hand increase in ALP is shown to correlate with the improvement in bone mass densitometry during treatment with parathyroid hormone analogues in osteoporosis." (PMID 25806360, 2015). "Randomized controlled trials (RCTs) comparing PTH analogues combined bisphosphonates with PTH for osteoporosis were analyzed." (PMID 26402797, 2015). "This mineral, which is present in milk, is essential in childhood, and its deficit dietary intake is involved in bone resorption mediated by the parathyroid hormone (PTH), which causes reduced bone mass and osteoporosis in adulthood." (PMID 26694443, 2015). "In the 2000s, daily injections of teriparatide (parathyroid hormone; PTH1–34) and full-length PTH (PTH1–84) were approved for the treatment of osteoporosis." (PMID 25911187, 2015). "Current treatment options for post-menopausal osteoporosis target either the osteoclast (i.e., anti-resorptive bisphosphonates and Denosumab) or the osteoblast (i.e., anabolic parathyroid hormone)." (PMID 25993011, 2015).
osteoporosis (continued). "Vitamin D replacement is recommended when 25(OH)D is lower than 10 ng/mL; for values ranging between 10 and 20 ng/mL, supplementation is recommended only for patients with osteomalacia, osteoporosis, or increased PTH." (PMID 26000302, 2015). "Previous studies showed that PTH strengthens vertebra in monkeys and humans, resulting in reduced rates of vertebral fractures in postmenopausal women with osteoporosis." (PMID 26466092, 2015). "Since PTH has been approved for the treatment of osteoporosis, a number of questions have arisen and PTH, in combination with other antiresorptive agents, has also been used for the treatment of osteoporosis." (PMID 26034928, 2015). "In bone metabolism, vitamin D increases the plasma levels of calcium and phosphorus, regulates osteoblast and osteoclast the activity, and combats PTH hypersecretion, promoting bone formation and preventing/treating osteoporosis." (PMID 24747593, 2014). "Moreover, PA patients showed higher plasma PTH, lower serum 25(OH)-vitamin D levels, higher prevalence of vitamin D deficiency (65% versus 25% and 25%; P < 0.001), and higher prevalence of osteopenia/osteoporosis (38.5 and 10.5%) than EH (28% and 4%) and NS (25% and 5%), respectively." (PMID 24864141, 2014). "Teriparatide, a recombinant PTH, is an anabolic treatment for osteoporosis that increases bone density." (PMID 25202461, 2014). "Restoration of lost bone is a major goal of osteoporosis treatment, to which end a variety of bone-anabolic agents, including once-a-day parathyroid hormone (PTH) and strontium ranelate, have been developed." (PMID 25757219, 2014). "We were unable to provide data about Vitamin D levels, parathyroid hormone and markers of both bone synthesis and re-absorption; future studies need to clarify the possible mechanisms of osteoporosis in NCWS." (PMID 25430806, 2014). "In osteoporosis, therapy with PTH in terms of one daily injection has been marketed as a bone anabolic treatment as it causes bone anabolic effects on trabecular bone." (PMID 25101193, 2014). "PTH1-34, a recombinant human parathyroid hormone analog containing the 34 residues, is currently used as an anabolic drug to treat osteoporosis." (PMID 24705625, 2014). "In the last decade, PTH has been found to be an important factor for bone remodeling, and injection of PTH has been approved for treatment of osteoporosis." (PMID 23788688, 2013). "Low calcium levels lead to increased parathyroid hormone (PTH) production, which increases calcium absorption from the bone, resulting in osteoporosis." (PMID 28197445, 2013). "PTH has been successfully used in the treatment of osteoporosis, and the positive effects on bone formation have been mainly attributed to the increased population of osteoblasts." (PMID 23788688, 2013). "And Teriparatide, the human recombinant parathyroid hormone 1–34, has been demonstrated to be a new and promising way for severe osteoporosis treatment for its function on bone regeneration." (PMID 23431296, 2013). "Some clinical studies indicate that a daily subcutaneous injection of PTH stimulates the development of new bone, increases bone mass in patients with osteoporosis and reduces the incidence of fractures in postmenopausal women." (PMID 23286544, 2013). "PTH stimulated both mineral apposition rate and bone formation rate resulting in increased bone mass, consistent with the reported effects of PTH in the treatment of both post menopausal and glucocorticoid-induced osteoporosis." (PMID 22916188, 2012). "Intermittent administration of parathyroid hormone (PTH) dramatically increases bone mass and currently is one of the most effective treatments for osteoporosis." (PMID 23300521, 2012). "While continuous administration of parathyroid hormone (PTH) causes bone loss, current interest in PTH focuses on its ability to strongly augment bone mass in severe osteoporosis patients by intermittent administration." (PMID 23300521, 2012).
osteoporosis (continued). "Intermittent treatment with parathyroid hormone (PTH) is another therapeutical approach for osteoporosis and activates the third major signaling pathway in bone regeneration." (PMID 23028809, 2012). "Although effective in the treatment of osteoporosis, daily injection of PTH for a period of 1–2 years is required." (PMID 22766833, 2012). "The main strenght of the study is that this is the first study to determine a cut-off PTH value, which affect the success of the bisphosphonate treatment in patients with osteoporosis." (PMID 23227959, 2012). "There are shared multiple pathophysiological mechanisms for heart failure and osteoporosis, through HF neuroendocrine activation matrix protein abnormalities, parathyroid hormone, adiponectin and leptin, etc." (PMID 22957004, 2012). "Primary hyperparathyroidism (PHPT) is a common endocrine disorder characterized by increased levels of serum calcium and parathyroid hormone (PTH) and symptoms of e.g. osteoporosis, kidney stones, psychological disturbances or cardiovascular disease." (PMID 22606260, 2012). "In terms of residual effects after discontinuation, bisphosphonates are distinct from other anti-osteoporosis agents including estrogen, raloxifene, parathyroid hormone, and receptor activator of NF-κB ligand (RANKL) inhibitors, such as denosumab." (PMID 22161728, 2012). "Taken together, these results suggest a novel mechanism for the therapeutic effect of PTH on osteoporosis and an important role of EGFR signaling in mediating PTH's anabolic actions on bone." (PMID 23300521, 2012). "The aim of this study was to evaluate the effects of PTH versus bisphosphonates on BMD for the treatment of osteoporosis." (PMID 22022584, 2011). "Most studies in osteoporosis treatment, however, attribute the anabolic actions of PTH to increased osteoblast activity." (PMID 21857768, 2011). "We conclude that the bone-formation agent PTH substantially increased BMD of the lumbar spine compared to bisphosphonates as indicated in the current clinical reports on osteoporosis treatment." (PMID 22022584, 2011). "The intermittent administration of PTH gained more importance in the last decade as a possible alternative for the treatment of osteoporosis and prophylaxis of fractures." (PMID 21603135, 2011). "Both low D3 and high PTH are important parameters in the diagnosis and treatment of osteoporosis in the DVO guidelines." (PMID 21849030, 2011). "Parathyroid hormone (PTH) function as immunologic mediator has become interesting with the recent usage of PTH analogue (teriparatide) in the management of osteoporosis." (PMID 20886005, 2010). "PINP is currently used to monitor the response to parathyroid hormone (PTH) treatment for osteoporosis." (PMID 20359335, 2010). "The striking clinical benefits of intermittent parathyroid hormone in osteoporosis have begun a new era of skeletal anabolic agents." (PMID 20981340, 2010). "Low levels of vitamin D lead to compensatory elevation of parathyroid hormone (PTH), which can cause lowering of bone mineral density (BMD) and eventually osteoporosis with fragility fractures or osteomalacia." (PMID 19152676, 2009). "Low-dosage intermittent parathyroid hormone (PTH) treatment has an anabolic effect on the skeleton and this ability makes PTH a promising therapeutic treatment for osteoporosis." (PMID 19747396, 2009). "Recombinant human parathyroid hormone (rhPTH) and recombinant bioactive fragments of human PTH are emerging as a unique new class of treatment options for osteoporosis." (PMID 19995322, 2009). "Accordingly, some anabolic and anti-resorptive agents, such as parathyroid hormone (PTH) and bisphosphonate, are used to treat osteoporosis patients." (PMID 19884996, 2009). "Although anabolic agents improve bone mass by stimulating osteoblast-mediated bone formation, only a single anabolic agent, parathyroid hormone 1–34 is available to treat osteoporosis at present." (PMID 18779865, 2008).
osteoporosis (continued). "Teriparatide, the recombinant 1-34 fragment of human parathyroid hormone (rhPTH1-34) differs from the other therapeutic options for treating osteoporosis, such as bisphosphonates or calcitonin, which act by reducing bone reabsorption." (PMID 19099162, 2008). "Elevated PTH, in turn, leads to calcium resorption or calcium withdrawal from bone, leading to demineralization of the bone and bone disease (i.e., osteoporosis)." (PMID 15706763, 1997). "Parathyroid hormone (PTH) serves as a key regulator of bone remodeling, while elevated plasma homocysteine-an established marker of vascular injury and skeletal fragility-has been implicated in osteoporosis." (PMID 42224245, 2026). "This trend may reflect increased awareness of osteoporosis assessment, leading to more frequent serum PTH and calcium testing." (PMID 41509026, 2026). "The findings of this study may provide new insights into optimizing PTH treatment for patients with osteoporosis by targeting cellular senescence in the bone microenvironment." (PMID 41432314, 2026). "Emerging concepts, such as intermittent PTH administration, an established treatment in osteoporosis, illustrate the potential for interventions that may restore mineral balance and improve skeletal integrity in selected CKD populations." (PMID 41852575, 2026). "Therapeutically, manipulating endosomal trafficking - via dynamin inhibitors or lysosomal escape modulators - could optimize PTH analogs for sustained anabolic benefits in osteoporosis 156-160." (PMID 40860192, 2025). "The key treatments for osteoporosis are antiresorptive drugs such as bisphosphonates, hormone replacement therapy, raloxifene, calcitonin, denosumab, as well as anabolic hormone analogs of parathyroid hormone (PTH), such as teriparatide." (PMID 40688824, 2025). "Consequently, a goal of ongoing research is to uncover the underlying molecular mechanisms driving the anabolic and catabolic effects of PTH to thereby secure more effective therapeutic alternatives for osteoporosis." (PMID 40153305, 2025). "The bioavailability of PTH, relative to subcutaneous injection, was 100%, and the PTH-loaded MNs effectively preserved bone density in a rat osteoporosis model without causing skin irritation." (PMID 40336019, 2025). "It is still unclear whether PTH has a beneficial short-term effect on the early healing of bone and soft tissue around implants in individuals with osteoporosis." (PMID 40507663, 2025). "Moreover, Ca, P, and vitamin 25 OH D levels were lower, while ALP and PTH levels were higher in patients with TM and osteoporosis." (PMID 40095502, 2025). "PTH, PTH analogs, and intermittent administration of PTH have been employed to treat osteoporosis." (PMID 40171106, 2025). "Furthermore, this study revealed a notable correlation between PTH levels and osteoporosis, highlighting an interplay between hormonal regulation and skeletal health (356.03 pg/mL vs. 297.64 pg/mL; p < 0.05)." (PMID 39941666, 2025). "In corroboration of these molecular mechanisms, intermittent PTH exposure has been exploited therapeutically (PTH-analog administration in osteoporosis), having been documented to reduce osteocyte sclerostin expression, while simultaneously increasing bone mass." (PMID 41227247, 2025). "Intermittent PTH exposure, such as in osteoporosis treatments, has been shown to have anabolic effects on bone, which might indirectly benefit muscle by enhancing bone-derived signaling molecules and providing mechanical support." (PMID 40806191, 2025). "The routine therapeutic drugs for osteoporosis include BPs, selective estrogen receptor modulators, and parathyroid hormone analogs, matched to the intervention of osteoporosis under different etiologies, fulfilling ideal efficacy while accompanied by certain adverse effects." (PMID 40741168, 2025).